RNU6-1197P (RNA, U6 small nuclear 1197, pseudogene)
Gene: Small nuclear RNA gene on chromosome 8 (74,079,537 to 74,079,643, forward strand). Ensembl gene ENSG00000212485.
Homologues: Orthologues: chimpanzee U6 (100% identical), macaque U6 (88% identical). Paralogues in human: RNU6-1309P (80% identical), RNU6-175P (80% identical), RNU6-343P (80% identical), RNU6-1020P (79% identical), RNU6-1094P (79% identical), RNU6-11P (79% identical), RNU6-28P (79% identical), RNU6-37P (79% identical), RNU6-45P (79% identical), RNU6-668P (79% identical), RNU6-1123P (79% identical), RNU6-1164P (79% identical), and 1284 more.